EPOR (erythropoietin receptor)
Diseases named in the same sentence as EPOR in open-access papers (continued):
Sharing a sentence is not in itself a finding about the gene and the disease.
tumor (continued). "Other binding studies suggested that EpoR could be detected on some non-hematopoietic tumor-cell lines." (PMID 24337485, 2014). "We used the polyclonal antibody (M-20) previously shown to have a reliable specificity to identify the EpoR by Western blot and immunohistochemistry, since the anti-EpoR antibody (C-20 Santa Cruz Biotech) has been reported to cross-react with HSP70, which is also highly expressed in tumor tissue." (PMID 23052842, 2013). "Using skin as a negative control to detect false-positives, and in concordance with previous tissue western results, no EpoR protein was detected in normal tissues from colon, lung, breast, larynx, tongue or ovary and there was no EpoR detected in the corresponding, matched tumor tissues." (PMID 23861852, 2013). "The phosphorylated cytoplasmic tail of EPOR acts as a docking site for proteins that contain Src-homology 2 (SH2) domains, for example STAT1, STAT3 and STAT5a/b, and initiates a cascade of signalling pathways that either promote erythropoiesis or tumour progression, depending on the target site." (PMID 23305401, 2013). "Studies using this antibody have indicated that many tumour cell lines express low-to-undetectable levels of EpoR and that any EpoR present is not functional (exposure of the cell lines to Epo does not activate signalling molecules such as STAT5 that function downstream of EpoR)." (PMID 22395661, 2012). "EPOR rather than EPO may be upregulated by hypoxia in the tumor bed, and the high expression of EPOR in the tumor tissue may promote neck lymph node metastasis." (PMID 22639817, 2012). "We concluded that EpoR-positive PDAC cells are equipped to respond to Epo but sol-EpoR might antagonize Epo signaling, with higher Epo having a greater chance of overcoming sol-EpoR and reaching tumor cells in vitro and in sEpohigh patients." (PMID 21829709, 2011). "Overall, the weight of preclinical evidence does not support a role for EpoR in tumour growth." (PMID 20051958, 2010). "Translocation of EpoR to the cell surface is an inefficient process (less than 1% of total cellular EpoR molecules are produced on the cell surface); thus, EPOR transcription and EpoR protein synthesis does not always lead to cell-surface expression of functional EpoR in tumour cells." (PMID 18349818, 2008). "None of the tumours with amplified EPOR contained EPOR in amplicons <1 Mb." (PMID 18349818, 2008). "Although EpoR mRNA was detected in some tumour lines, no EpoR could be detected on the cell surface using 125I-Epo binding studies." (PMID 18349818, 2008). "Treatment with darbepoetin did not influence the proliferation rate of the EpoR-expressing tumour cells under either aerobic or hypoxic growth conditions, indicating that the receptor may be nonfunctional on these cells." (PMID 15999100, 2005). "Darbepoetin alfa treatment alone did not modulate the growth of the EpoR-expressing tumour cells." (PMID 15999100, 2005). "Importantly, these studies could not address erythropoietin-dependent EpoR function in tumor tissue." (PMID 25807104, 2015). "However the EpoR transcript levels were significantly below that found in positive controls (cells or tissues containing Epo-responsive cell types) with no elevation in tumor compared to nontumor tissues." (PMID 23861852, 2013). "Although we could not exclude the inertness of Epo towards the tumor cells under the studied conditions, we hypothesized that a soluble isoform of EpoR (sol-EpoR) might block Epo signaling by binding of Epo and thereby decreasing receptor-mediated signal transduction." (PMID 21829709, 2011). "Given the precise role of rhEpo in human cancers, particularly tumor progression and recurrence, is not well understood, clinical and basic research studies are still necessary to define signaling pathways activated by rhEpo/EpoR within nonhematopoietic cancer cells." (PMID 22188703, 2011).
tumor (continued). "Moreover, a study found that primary tumour cells from human breast, non-small cell lung, colorectal, and ovarian tissues, including the HT-29 colorectal cell line, express minimal to no functional erythropoietin receptor (EpoR) protein and do not show Epo-induced signalling pathways." (PMID 41514679, 2026). "The CMT cells were positive for the epithelial marker, cytokeratin-8; tumor markers, VEGF, HER-2, MMP-2, HIF-1α, and Bcl-2; and hormone receptors, PGR and EPOR, while negative they were for estrogen receptor, ER." (PMID 30410940, 2018). "Though tumor samples exhibited a broad range of cell-surface expression of EGFR, c-Met, and IGF-1R, no cell-surface erythropoietin receptor was detected in tumor cells from the 186 tumors examined (by flow cytometry or Western blot)." (PMID 25807104, 2015). "EPOR mRNA was overexpressed in all OSCC tissue samples, indicating a higher level of EPOR in the tumor tissue than in the adjacent non-tumor oral tissue after normalization using GAPDH." (PMID 22639817, 2012). "We could not identify characteristic distinctions between EpoR-positive and EpoR-negative cells (e.g., specific localization within the tumor or near vessels), nor was there a correlation with lymph node-positive N1 status of tumor or grade of tumor differentiation." (PMID 21829709, 2011). "Using this platform, we explored γc cytokine–receptor pairings that either do not occur in nature, are rarely studied in anti-tumour properties (such as IL-10, IFNs) or involve receptors not naturally expressed on T cells (for example, IL-20R, IL-22R, GCSFR, EPOR)." (PMID 40804519, 2025). "The recombinant human erythropoietin competes with ephrin-B2 for binding to EPHB4, and therefore, the tumor progression might be mediated via EPO-induced phosphorylation of EPHB4 and subsequent activation of downstream signaling, independent of the EPOR." (PMID 35694408, 2022). "However, relative mRNA expression levels of EPOR and MXD1 were not significantly different between normal and tumor cases." (PMID 34277626, 2021). "All this evidence suggests that EPOR, like EPO, may play a non-negligible role in tumor immunity." (PMID 35359375, 2022). "Although indirect effects on tumours induced by increased RBC production are theoretically possible, preclinical data to date suggest that tumour cells either do not express EpoR or express low levels of EpoR molecules that are non-functional and/or are not present at the cell surface." (PMID 22395661, 2012).
cancer (71 papers, 2001 to 2026). A tumor composed of atypical neoplastic, often pleomorphic cells that invade other tissues. "For the five cancers associated with OS, EPOR expression in COAD was positively associated with 27 immune checkpoint genes, and that in KIRC was associated with 19 immune checkpoint genes." (PMID 35359375, 2022). "The over-expression of EPOR-R129C in cancer cells was specifically associated with the increased phosphorylation of ERK1/2 both in vitro and in vivo." (PMID 17579721, 2007). "Also, the murine mitochondrial mtDNA in shEPOR tumors was ~2 times lower than in shSCR tumors (p<0.001), confirming that both human A549 shEPOR cancer cells and adjacent murine stromal cells in EPOR-deficient tumors had fewer mitochondria than in shSCR tumors." (PMID 36052260, 2022). "Increased EPOR expression was also linked to reduced response to anti-cancer treatment." (PMID 25426117, 2014). "In spite of a growing amount of in vitro and in vivo studies that associate the presence of EpoR with the promotion of cancer cells proliferation and invasion, a linear correlation between EpoR activation and an efficient responsiveness to exogenous EPO administration has not been established." (PMID 23052842, 2013). "EPOR is associated with numerous diseases such as urological disorders, musculoskeletal or connective tissue disorders, immune system disorders, endocrine system disorders, hematologic disorders, cancer, or benign tumors, reflecting its broad distribution, and it plays a key role in the human body." (PMID 35359375, 2022). "In addition, in our findings, EPOR was a protective factor in a subset of specific cancers and a risk factor in another subset of cancers, but the mechanism of action of EPOR in different cancers needs to be further explored." (PMID 35359375, 2022). "The findings reveal that reducing SOCS6 increases cancer cell survival and migration, while changes in EPOR expression influence SOCS6 levels and cell survival differently depending on the cell type." (PMID 41514679, 2026). "The erythropoietin receptor (EPOR) is a cytokine receptor with three distinct structural domains that plays a crucial role in cancer development." (PMID 41514679, 2026). "EPOR’s presence in cancer cells highlights the complex network of signalling channels controlling cellular activity." (PMID 41514679, 2026). "Its potential therapeutic effects have been a topic of concern, with erythropoiesis-stimulating agents (ESAs) targeting EPOR to improve anaemia in cancer patients after chemotherapy." (PMID 41514679, 2026). "The convergence of HIF-1α and EPO/EPOR signaling further underscores their complex influence on cancer progression." (PMID 38542288, 2024). "The notion that some tumors express functional EPOR is based on the binding of EPO to EPOR in cancer cells in vitro and in vivo." (PMID 36052260, 2022). "EPOR-deficient A549 tumors had lower pAKT levels than control tumors and AKT is often phosphorylated by EPO/EPOR in other (cancer) cells, supporting their growth and regulating mitochondrial biogenesis." (PMID 36052260, 2022). "First, we used 33 cancer datasets as the study unit (n = 9,493) and the EPOR high-expression group had a longer OS compared to the EPOR low-expression group." (PMID 35359375, 2022). "The average frequency of EPOR alterations in pan-cancer was only 1.9%, but we unexpectedly found that EPOR gene alterations in pan-cancer prolonged DFS in patients (p = 8.53e-4) and that the frequency of EPOR alterations in OV was higher, at around 8%." (PMID 35359375, 2022). "We further explored the prognostic impact of EPOR on patients with each type of cancer, using gene expression profile data and univariate regression analysis to plot forest plots, and KM survival curves for tumors with significantly affected OS." (PMID 35359375, 2022).
cancer (continued). "After combining the GTEx database, EPOR was found to be expressed at lower levels in 18 cancer tissues than normal tissues, including BRCA, CESC, and COAD, and at higher levels in CHOL, GBM, HNSC, LGG, SKCM, and TGCT." (PMID 35359375, 2022). "After combining the GTEx database, EPOR expression was found to be downregulated in 18 cancer tissues and upregulated in 6 cancer tissues." (PMID 35359375, 2022). "Nevertheless, further research must be performed to prove the contribution of AKT, MAPK, and their cooperation regarding the EPO/EPOR or constitutive EPOR in cancer cells." (PMID 34299300, 2021). "Studies were obtained using the following keywords: “STAT5” or “erythropoietin” or “erythropoietin receptor” and “erythropoiesis” or “cancer cell” or “normal cell” or “signaling”." (PMID 34281163, 2021). "Studies focus on EPOR signaling in cancer cells, which interacts with apoptotic pathway, hypoxia pathway and anticancer agents." (PMID 32015330, 2020). "EPO increases the expression of EPOR in cancer cells, thereby increasing cancer cell growth and metastasis." (PMID 32908942, 2020). "In this study we investigated the methylation status of exon 1 of EPOR gene in selected human cancer cell lines." (PMID 30606107, 2019). "It is also postulated that uptake of EPO-TAMNLC by cancer cells is through EpoR-mediated endocytosis, otherwise known as clathrin-mediated endocytosis." (PMID 31291309, 2019). "EPOR positive cancer cell line UT-7 revealed the highest 96% methylation profile of monitored sequence." (PMID 30606107, 2019). "The human and experimental studies have revealed that EPO and EpoR can co-express in a diversity of human malignancies and the EPO/EpoR signaling is involved in cancer cell proliferation, inhibition of apoptosis, and invasiveness." (PMID 31217907, 2019). "Like other cancer types, co-expression of EPO and EPOR has been reported in NSCLC and was associated with poor survival of NSCLC patients." (PMID 29137269, 2017). "Over the last decade, growing evidences have shown the co-expression of EPO and EPOR are connected to cancer cell growth, migration, and invasiveness in various human malignancies." (PMID 29137269, 2017). "Response to erythropoietin was stronger in DLD-1 xenografts, which confirms the involvement of EpoR in promoting the cancer process." (PMID 27543111, 2016). "From the point on that we first reported that normal and malignant female reproductive organs express Epo and EpoR mRNA, there has been accumulating evidence that the Epo-EpoR pathway is substantially involved in cancer progression." (PMID 25874769, 2015). "Clinical trials with reported adverse effects of chronic erythropoiesis-stimulating agents (ESAs) treatment as well as clinical studies exploring the prognostic significance of EPO and EPOR expression in cancer patients are reviewed." (PMID 25426117, 2014). "The expression of EPOR isoforms was paralleled with the invasiveness of cancer and epithelial-like breast cell lines included in the current study." (PMID 24294184, 2013). "The existence of the EPO/EpoR signaling pathway has been recently observed in a wide range of tumors and cancer cell line, but its role and true function in the context of cancer biology are still a matter of controversy and currently under investigation." (PMID 23052842, 2013). "The other school argues that the binding of rhEPO with EPOR would enhance the progression of cancer." (PMID 23305401, 2013). "Although EPOR is widely expressed in malignant tumors including human NSCLC, the significance of EPOR signaling in this malignancy is not fully elucidated." (PMID 24155958, 2013). "EpoR activation is considered to influence cancer cell growth in terms of stimulated proliferation, decreased apoptosis and increased resistance to therapy." (PMID 23077460, 2012). "Thus, EPOR plays a pivotal role in cancer development and progression, with its intricate relationship highlighting its importance in tumourigenic environments." (PMID 41514679, 2026).
cancer (continued). "EPOR, the erythropoietin receptor, is best known for its role in erythropoiesis; however, accumulating evidence points to its involvement in cancer biology." (PMID 40895144, 2025). "Researchers have found that the increased expression of EPOR may promote cancer cell survival through bcl-2 and reduce the effectiveness of chemotherapy with cisplatin." (PMID 38542288, 2024). "EPOR plays an important role in the progression of numerous cancers and can be used as a prognostic marker, but the precise mechanism of EPOR action on cancer cells needs to be further investigated." (PMID 37239828, 2023). "We used EPOR knockdown cancer cells to generate in vivo xenografts and to analyze the role of EPOR in the control of cellular respiration in tumors with high-resolution respirometry and mitochondrial biogenesis by using in vitro and in vivo cell biological methods." (PMID 36052260, 2022). "In addition, the enrichment analysis revealed that EPOR is involved in multiple cancer-related pathways." (PMID 35359375, 2022). "We asked whether the activation of the EPO/EPOR axis controls mitochondrial metabolism in cancer cells by inducing NOS expression, and thereby regulating mitochondrial biogenesis." (PMID 36052260, 2022). "The cBioPortal database showed that EPOR was genetically altered in 27 of 33 cancers, and gene amplification was the most common type of genetic alteration in EPOR, with the highest frequency of EPOR alteration in OV at around 8%, with an average alteration frequency of 1.9%." (PMID 35359375, 2022). "The general situation of EPOR expression in cancer provided a valuable clinical reference." (PMID 35359375, 2022). "This study intended to perform a pan-cancer analysis of EPOR by bioinformatics methods." (PMID 35359375, 2022). "It has been claimed that myeloid-derived suppressor cells (MDSCs), which are precursors of DCs, macrophages, or granulocytes, have the ability to negatively regulate the immune response in cancer, with a subpopulation of monocytic MDSCs mediated by the EPOR-mediated Jak2/GATA3/STAT3 pathway induced." (PMID 35359375, 2022). "We provide evidence that EPOR contributes to the regulation of mitochondria in cancer cells." (PMID 36052260, 2022). "Indeed, EPORs of cancer cells are located either on the membrane surface or as a soluble intracellular forms, and apart from the classical EPOR, ephrin-type B receptor 4 (EPHB4) as an alternative EPO binding form was identified in malignant cells." (PMID 34299300, 2021). "During this process, EPO/EPOR pathway is believed to promote cancer progression." (PMID 32015330, 2020). "Although the expression of CD131 on cancer cells remains unclear, the expression of EPOR has been verified both on mRNA and protein level." (PMID 32015330, 2020). "Additionally, M1/M2 marker expression profiles of CD163+EPOR+ TAMs suggested a distinctive effect in supporting cancer progression." (PMID 32908942, 2020). "In our study, we focused on the monitoring of CpG sites around the first exon (+ 1/+ 125) of EPOR gene (NG_021395.1) in various cancer cell lines because of large EPOR promoter homogeneity with other genes and very high homogeneity and tandem repetitions in EPOR promoter itself." (PMID 30606107, 2019). "We outlined the methylation status of all selected cancer cell lines in exon 1 of EPOR gene and these results could benefit future investigations." (PMID 30606107, 2019). "High mRNA and protein levels of EPO and EPOR have been reported in several cancer cell lines." (PMID 28430808, 2017). "Since EPO is a survival factor in erythroid progenitor cells, we investigated whether EPOR knockdown in cancer cell lines would lead to apoptosis." (PMID 28418910, 2017). "Furthermore, expression of the EPO receptor (EPOR) has been detected in some tumors and cancer cells including NSCLC cells." (PMID 27494133, 2016). "In conclusion, these results show that both EpoR-positive and EpoR-negative cancer cells could be regulated by exogenous Epo." (PMID 27543111, 2016).